Y_RNA (Y RNA )
Gene: Miscellaneous RNA gene on chromosome 1 (240,341,385 to 240,341,477, forward strand). Ensembl gene ENSG00000252317.
Homologues: Paralogues in human: RNY1 (80% identical), Y_RNA (80% identical), RNY1P12 (78% identical), Y_RNA (78% identical), Y_RNA (77% identical), Y_RNA (76% identical), Y_RNA (75% identical), RNY1P11 (74% identical), Y_RNA (74% identical), RNY1P8 (73% identical), Y_RNA (73% identical), RNY1P7 (72% identical), and 91 more.